MTOR (mechanistic target of rapamycin kinase)
Diseases named in the same sentence as MTOR in open-access papers (continued):
Sharing a sentence is not in itself a finding about the gene and the disease.
Autoimmunity (continued). "However, excessive B cell mTORC1 signaling is detected as a prevalent factor in mice models of autoimmunity, and elevated autophagy due to mTOR inhibition, along with antigen presentation by B cells, appears to amplify autoimmunity in mice models." (PMID 35897651, 2022). "Lastly, treatment response to co-stimulation inhibiton and calcineurin/mammalian target of rapamycin (mTOR) inhibiton may suggest contribution of autoimmunity to inflammation in PsA." (PMID 33581710, 2021). "Recently, redox-controlled activation of the mechanistic target of rapamycin (mTOR) has been recognized to play a critical regulatory role in the immune system, which highly implies that mTOR is a key bridge of metabolic stress and autoimmunity." (PMID 31016198, 2019). "This tunable nature of mTOR signaling in Treg cells may offer a therapeutic strategy to modulate Treg-cell responses to selectively alter the conventional T-cell responses in autoimmunity, infectious diseases, and cancer." (PMID 29844370, 2018). "In this way, inactivation of the mTOR pathway could also led to a lower activity of Tregs, and subsequent autoimmunity problems." (PMID 30487748, 2018). "As mTOR inhibitors have entered clinical practice as anticancer drugs and are under evaluation as vaccine adjuvants, adjuncts to treating autoimmune disorders and to extend lifespan and healthspan, understanding the range of mTOR effects on immunity is crucial." (PMID 26315673, 2015). "Although the precise role of the encoded protein remains largely unknown, the function of DDIT4L in autoimmunity may be related to the negative regulation of mTOR." (PMID 26057447, 2015). "Indeed recent work has uncovered a strong link between the mTOR pathway, Treg function and autoimmunity." (PMID 18980674, 2008). "However, the role of Rab4A-mediated endosome traffic beyond mTOR activation, T-cell lineage development and autoimmunity remain unknown." (PMID 38519468, 2024). "However, there is another side to mTOR, autophagy, B cells, and autoimmunity." (PMID 35897651, 2022). "Immune dysregulation, specifcally autoimmunity, is a commonality that might explain the pathogenesis of HL in addition to overactive key oncogenic signaling pathways such as the mammalian target of rapamycin (mTOR) pathway." (PMID 24395633, 2014). "Although leptin resistance presented early in BWF1 mice can slow-down the progression of autoimmunity, our results suggest that sustained insulin stimulation of organs, such as liver and probably kidneys, facilitates the over-expression and activity of mTOR and the development of SLE." (PMID 23226562, 2012). "After diagnosis, 12 patients were started on mTOR inhibitors, four on abatacept, and two on JAK inhibitors, with better control of autoimmunity." (PMID 41142805, 2025). "Conversely, the AD-A group demonstrated upregulation of several transcripts implicated in tumorigenesis (CAB39), intracellular signaling (CAB39), autoimmunity (IFIT3), and mTOR signaling (DEPTOR)." (PMID 41010010, 2025). "Modifying immune responses by targeting metabolic pathways, such as the mTOR and AMPK pathways, is useful in conditions governed by autoimmunity and inflammation." (PMID 39996755, 2025). "mTOR plays a crucial role in the relationship among HMGB1, activation of mDCs, and autoimmunity in SLE." (PMID 34164408, 2021). "Our findings on DCAC-induced increases in phos-ERK and phos-AKT/mTOR are consistent with elevated ROS/RNS observed in our previous in vivo studies and provide further support to the role OS in TCE-mediated autoimmunity." (PMID 30596806, 2018). "In our study, we showed that ATP-competitive dual mTOR inhibitor AZD8055 exhibited potent immunosuppressive properties and was used therapeutically in countering autoimmunity and preventing allograft rejection." (PMID 27128484, 2016).
Autoimmunity (continued). "Although the quantity of protein foods on the WahlsElim modeled diets was higher than the HEP, the percent energy from protein was within the AMDR range and was lower than most Paleo diets to minimize the negative effects of mTOR on autoimmunity." (PMID 30832289, 2019).
myocardial ischemia (60 papers, 2014 to 2025). A disorder of cardiac function caused by insufficient blood flow to the muscle tissue of the heart. "Researchers have found an association between AKT/mTOR mediated autophagy and myocardial ischemia/reperfusion injury." (PMID 34460437, 2021). "Another study showed that TXL reduced cardiomyocyte apoptosis by promoting AMPK phosphorylation and decreasing mTOR phosphorylation, activating autophagy during post-infarction cardiac ischemia." (PMID 41199814, 2025). "Medioresinol was selected for further study and shown to significantly improve oxidative stress and inflammatory response in myocardial ischemia-hypoxia model cells by activating the PI3K/AKT/mTOR pathway." (PMID 39331625, 2024). "We examined the effect of rapamycin (RAPA, mTOR inhibitor) on cardiac remodeling and inflammation following myocardial ischemia/reperfusion (I/R) injury in diabetic rabbits." (PMID 37240345, 2023). "Previous experimental studies reported that RHO has an anti-inflammatory impact on myocardial ischemia by inhibiting the PI3K/Akt/mTOR pathway in vivo and the TLR4/NF-κB signaling pathway." (PMID 37888707, 2023). "Studies have revealed the modulation of cardioprotection of Chuanxiong in myocardial ischemia injury through the activation of PI3K/Akt/mTOR signaling pathway." (PMID 36517846, 2022). "The mammalian target of rapamycin (mTOR) is a protein kinase that regulates autophagy during myocardial ischemia." (PMID 35370737, 2022). "For example, recent research has found that curcumin shows a significant protective effect in myocardial ischemia–reperfusion by activating the PI3K/AKT/mTOR signaling pathway and inhibiting inflammation, apoptosis, and oxidative stress." (PMID 35630767, 2022). "For example, AMPK/mTOR signaling pathway was involved in the protection of melatonin against myocardial ischemia/reperfusion injury." (PMID 34709566, 2022). "Inhibition of GSK3β stimulated mTOR signaling and inhibited autophagy through a rapamycin-sensitive mechanism during myocardial ischemia and IR." (PMID 34819832, 2021). "This increase in SGLT1 expression can be linked to the increased phosphorylation of secondary messengers such as ERK 1/2 and the mammalian target of rapamycin (mTOR), involved in the signaling pathways of cardiac ischemia/hypertrophy." (PMID 34884494, 2021). "Both melatonin and choline limit excess autophagy by activating mTOR, which ultimately reduces the infarct area after myocardial ischemia-reperfusion." (PMID 33328993, 2020). "Previous studies have shown that HMGB1 regulates the PI3K/Akt/mTOR pathway in myocardial ischemia reperfusion injury and the ALI mouse model." (PMID 32636835, 2020). "Myocardial ischemia/reperfusion injury was attenuated by inhibiting autophagy via the AMPK/mTOR signaling pathway via adding metformin." (PMID 31737173, 2019). "Defective BCAA metabolism also further aggravates cardiac dysfunction and adverse remodelling following myocardial ischemia/reperfusion injury through triggering the mammalian target of rapamycin (mTOR) signalling pathway." (PMID 30626440, 2019). "Next, we set out to explore the role of the PI3K/Akt/mTOR signaling pathway in the protective effects of LLC against myocardial ischemia injury." (PMID 29651246, 2018). "In contrast to Shioi’s reports, we demonstrated here that TGC significantly inhibited the mTOR pathway, leading to increased autophagy in the context of myocardial ischemia." (PMID 29872406, 2018). "For example, in myocardial ischemia, the mTOR signaling pathway is inhibited by AMP-activated protein kinase (AMPK) that is activated by a reduction in cellular ATP levels." (PMID 30050390, 2018). "The results showed that MDRN could significantly improve oxidative stress and inflammatory response in myocardial ischemia-hypoxia model cells by activating the PI3K/AKT/mTOR signaling pathway, enhancing cell viability and mitochondrial membrane potential." (PMID 39331625, 2024).
myocardial ischemia (continued). "Moreover, mTOR exerts its functions in myocardial ischemia both by the AMP-activated protein kinase/mTOR and phosphatidylinositol-3-kinase/Akt/mTOR signalling pathways." (PMID 36815377, 2023). "Additionally, mTOR contributes to cardiomyocyte survival; inhibition of mTORC1 showed protection against cardiac ischemia/reperfusion injury, while dual mTOR inhibitors abolished cardioprotection after ischemic preconditioning." (PMID 34948382, 2021). "Contrary to our findings, HBOT preconditioning (2.5ATA, 1hr, one time per day for 14days) could reduce Beclin-1 and increased mTOR expression resulting in the inhibition of exaggerated autophagy in rats with myocardial ischemia reperfusion injury." (PMID 33861726, 2021). "Studies have shown that terpene glucoside protects the heart from ISO-induced myocardial ischemia by activating the phosphatidy linositol 3-kinase (PI3K)/AKT/mammalian target of rapamycin (mTOR) signaling pathway to improve cardiac energy metabolism and inhibit cardiomyocyte apoptosis." (PMID 32754038, 2020). "In contrast to the inhibition of mTOR by AMPK during myocardial ischemia, mTOR is activated during myocardial reperfusion through the inhibition of the glycogen synthase kinase-3β (GSK-3β)/tuberous sclerosis complex 2 (TCS2) pathway, resulting in decreased autophagy." (PMID 33328993, 2020). "Besides activating the NF-κB and MAPK pathways, recent studies also have demonstrated that HMGB1 regulates the PI3K/Akt/mTOR signaling pathway in myocardial ischemia/reperfusion injury and LPS-induced pulmonary inflammation in ALI models." (PMID 32636835, 2020). "Thus, we can infer that the PI3K/Akt/mTOR pathway is involved in the modulation of cardioprotection of LLC in myocardial ischemia injury." (PMID 29651246, 2018). "However, as with mTOR in cardiac ischemia, there is still uncertainty as to the role of mTOR in mediating cerebral stroke damage in vivo." (PMID 30594149, 2018). "Consequently, the downregulated mTOR signaling pathway in QDB can activate autophagy which is evidenced to be harmful for myocardial ischemia reperfusion." (PMID 25548593, 2014). "For myocardial ischemia/reperfusion injury and cardiomyopathy it induced, the mTOR pathway may protect cardiomyocytes against ferroptosis because of the reduction of ROS production, and Icariin attenuates ferroptosis by activating the Nrf2/HO-1 signaling pathway." (PMID 35476142, 2022). "In Myocardial ischemia/reperfusion injury, Hydroxysafflor yellow A can activate AMPK to reduce the NLRP3 inflammasome via blocking the mTOR pathway." (PMID 35873572, 2022). "Exosomes derived from MSC can also reduce myocardial ischemia/reperfusion injury by inducing cardiomyocyte autophagy via AMP-activated protein kinase (AMPK)/mTOR and Akt/mTOR pathways." (PMID 33086718, 2020). "However, in myocardial ischemia/reperfusion injury, myocardial-specific TXNIP is overexpressed and directly interacts with the autophagy regulatory factor Redd to inhibit mTOR, thereby aggravating cardiac ischemia/reperfusion injury." (PMID 36059548, 2022).
anemia (59 papers, 2010 to 2025). A reduction in the number of red blood cells, the amount of hemoglobin, and/or the volume of packed red blood cells. "The mammalian target of rapamycin (mTOR) inhibitors also cause anemia, characterized by profound microcytosis, via bone marrow suppression in a dose-dependent fashion." (PMID 35795334, 2022). "The risk of anemia following transplantation is compounded by immunosuppression with mTOR inhibitors or mycophenolic acid, although this effect is less marked in the presence of higher GFR." (PMID 24883202, 2014). "Underactive mTOR complexes cause a type of anemia that produces small red blood cells and is usually triggered by a lack of iron." (PMID 25201874, 2014). "mTOR has multifunctional role in inflammation; inhibition of mTOR causes distinct inflammatory side effects such as fever, pneumonitis, glomerulonephritis or anemia of chronic disease." (PMID 26219821, 2015). "Both mTOR inhibitors were associated with elevated lipid levels, mouth ulcers, edema, skin rashes, and hematological disturbances (thrombocytopenia, leukopenia, and anemia)." (PMID 24719752, 2014). "Similarly, the adverse events associated with the mTOR inhibitors were generally manageable; thrombocytopenia, neutropenia, and anemia were the most commonly reported hematologic toxicities." (PMID 21092307, 2010). "In contrast, models of IDA and phlebotomy-induced anemia indicate diminished mTOR signaling, partially via changes in the hypoxia-sensitive DDIT4/REDD1 pathway." (PMID 40863165, 2025). "Rapamycin increased hemoglobin in B6.TC/Rab4AQ72L and B6.TC/Rab4AQ72L-KO mice, suggesting that mTOR activation contributed to anemia in SLE." (PMID 38519468, 2024). "The AE pattern differs from those observed in previous clinical trials for other mTOR inhibitors, in which the most common AEs were stomatitis, anorexia, anemia, dyspnea, and pneumonitis." (PMID 38057772, 2023). "The most common mTOR inhibitor is sirolimus (rapamycin), which was shown to prevent bleeding and anemia in preclinical mouse models of HHT by controlling VEGFR2 and mTOR overactivation." (PMID 36504622, 2022). "Previous studies have demonstrated that microcytosis or anemia are induced in mTOR inhibitor-treated subjects." (PMID 35273970, 2022). "Notable, in advanced cancer patients, specific conditions affecting energetic efficiency, including insulin-resistance, anorexia, and anemia, are capable of inhibiting mTOR." (PMID 33809200, 2021). "Anemia, secondary to chronic gastrointestinal bleeding, was present in all patients in the mTOR inhibitor group before starting treatment." (PMID 33822054, 2021). "Prior to initiating therapy, all patients in the mTOR inhibitor group had anemia, and all but one had hypoalbuminemia." (PMID 33822054, 2021). "This condition was justified by as that L-leucine activate mTOR pathway and thus improves anemia in the DBA patients by promoting mRNA translation." (PMID 29745857, 2018). "Anemia usually appears within the first month of initiation of MTOR inhibitor and it persists throughout its course of therapy." (PMID 30155279, 2018). "Post-transplant anemia occurs in 12% to 76% of KTR and MTOR inhibitor is one of the frequent causes among these etiologies." (PMID 30155279, 2018). "Meanwhile, the abnormal activation of mTOR in erythrocytes led to anemia in mDNA mutant mice by inhibiting mitophagy in early erythroid progenitor cells and mitochondrial clearance in mature erythrocytes." (PMID 29967662, 2018). "It was reported that L-leucine, which increases translation via the mTOR pathway and the phosphorylation of S6K and 4E-BP, resulted in an improvement of anemia in zebrafish models of both DBA and del(5q) syndrome." (PMID 26961822, 2016). "Treatment of embryos with amino acid L-Leucine, a potent activator of the mTOR pathway and mRNA translation, has been shown to alleviate anemia in rps14 and rps19 morpholino knock-down zebrafish embryos." (PMID 26624285, 2015).
anemia (continued). "Agents targeted to the mammalian target of rapamycin (mTOR), which is associated with increased angiogenesis by binding to intracellular protein (FKBP-12) 8, are associated with fatigue, rash, anemia, and metabolic abnormalities 9,10." (PMID 25619758, 2015). "Boosting the activity of the mTOR complex leads to a type of anemia in which the cells are much larger than normal, and which is normally associated with inadequate amounts of folate and B12 vitamins." (PMID 25201874, 2014). "The frequent adverse events of the mTOR inhibitors are hematological, especially microcytic anemia, leukopenia, and thrombocytopenia." (PMID 23514595, 2013). "Glomerulonephritis and anemia secondary to a chronic inflammatory state have also been observed in patients treated with mTOR inhibitors, which is consistent with a pro-inflammatory role for rapamycin in some patients." (PMID 22685525, 2012). "Thrombocytopenia, neutropenia, and anemia are the most commonly reported hematologic toxicities reported during monotherapy with the mTOR inhibitors everolimus, temsirolimus, and ridaforolimus." (PMID 21092307, 2010). "Consequently, it was suggested that the mTOR pathway is involved in the pathogenesis of anemia, particularly because it relates iron availability to cell growth and hemoglobin synthesis during erythropoiesis." (PMID 40836330, 2025). "Furthermore, monomethyl auristatin inactivates the Akt/mTOR pathway and a classical side effect of mTOR inhibitors like rapamycin and temsirolimus is anemia due to eryptosis with erythrocyte shrinkage, membrane scrambling and release of phospholipids." (PMID 38039414, 2023). "According to the literature, mTOR inhibitor discontinuation due to anemia is rare." (PMID 36615165, 2023). "Leucine is a major amino acid in hemoglobin, and it can improve anemia via mTOR signaling and iron metabolism; thus, there could be a close correlation between leucine and hemoglobin during CCRT." (PMID 35804884, 2022). "However, long-term inhibition of mTOR activity can lead to inhibition of wound healing, anemia, proteinuria, pneumonia, and hypercholesterolemia." (PMID 34177563, 2021). "This study summarizes phenotypic features of patients with JPI and shows that treatment of JPI patients with mTOR inhibitors reduces disease progression, reduces need for colectomy and corrects hypoalbuminemia and anemia as surrogate markers of epithelial barrier dysfunction and bleeding." (PMID 33822054, 2021). "However, significant microcytosis is a unique characteristic of mTOR inhibitor-induced anemia reported in patients after kidney and heart transplantations, as well as in cancer patients." (PMID 34202704, 2021). "Importantly, IL-6 is considered a mediator of cancer anorexia and the main inducer of cancer anemia, and both conditions eventually inhibit the mTOR axis, thereby establishing a vicious cycle that augments muscle wasting." (PMID 33809200, 2021). "Moreover, in an inflammatory cytokine-induced model of anemia in human hematopoietic stem/progenitor cells, it was found that TNFα-induction of anemia occurs via inhibition of autophagy in an mTOR-dependent manner." (PMID 32195258, 2020). "p-AKT, p-mTOR and p-4E-BP1 expression were all associated with a shorter TNT in univariate analysis, either on their own or in combination, along with younger patient age, anaemia, elevated percentage of BM infiltration by hairy cells." (PMID 26893254, 2016). "Interestingly, among several kinds of adverse events, patients prioritized anemia and pneumonitis, which were two most common grade 3 or 4 adverse events from aromatase inhibitor plus mTOR inhibitor." (PMID 26558177, 2015). "Interestingly, the amino acid L-leucine ameliorates developmental defects and anemia associated with mouse and zebrafish models for DBA and 5q-Sydrome, through the mTOR pathway." (PMID 24098154, 2013).